CD83 (CD83 molecule)
Diseases named in the same sentence as CD83 in open-access papers (continued):
Sharing a sentence is not in itself a finding about the gene and the disease.
giant cell arteritis (2 papers, 2013 to 2019). "Anti-CD83 antibodies can be effective in other inflammatory settings, as demonstrated in a xenogeneic mouse model of giant cell arteritis (GCA)." (PMID 31231400, 2019).
graft versus host disease (2 papers, 2013 to 2023). An immune system disorder that occurs after allogeneic hematopoietic stem cell transplant and is a reaction of donor immune cells against host tissues. "The CD83-targeted chimeric antigen receptor (CAR) T cell targeted therapy was proposed based on the report by Shrestha and colleagues that CD83 was a novel target against graft-versus-host disease in AML patients undergoing bone marrow hematopoietic stem cell transplantation." (PMID 37596597, 2023).
hepatocellular carcinoma (2 papers, 2009 to 2019). A malignant tumor that arises from hepatocytes. "We have reported that the supernatant from human hepatocellular carcinoma (HCC) cells induced functional impairment of DCs as demonstrated by the downregulation of MHC class I and class II, CD80, CD86, and CD83 molecules." (PMID 20182533, 2009). "Moreover, in hepatoma-transplanted murine models, sFGL2 blockage promoted MHCII and CD83 expression and downregulated the expression of CD31, which is reportedly an immune-inhibitory marker on the DC surface." (PMID 31409352, 2019).
laryngeal carcinoma (2 papers, 2013 to 2016). Carcinoma that arises from the laryngeal epithelium. "The incompetence of DC-TCS, which express low levels of MHC molecules (e.g., HLA-DR) and maturation markers (e.g., CD83), may result from inhibition by the tumor milieu and fewer laryngeal cancer cell-secreted Ags." (PMID 26795730, 2016). "Our results prove that there is a relation between the presence of laryngeal cancer and the expression of B7H1, B7H4, CD200, and CD200R regulatory molecules on the CD83+ Mo-DC pulsed with autologous cancer cell lysates." (PMID 23632869, 2013).
lymphoma (2 papers, 2018 to 2020). A malignant (clonal) proliferation of B- lymphocytes or T- lymphocytes which involves the lymph nodes, bone marrow and/or extranodal sites. "Several types of lymphomas, such as HL, diffuse larger B‐cell lymphoma and chronic lymphocytic lymphoma, which have been reported as CD83+, also showed NF‐κB activation as a hallmark in their pathogenesis." (PMID 32685149, 2020).
malaria (2 papers, 2022 to 2023). Malaria is a serious and sometimes fatal disease caused by a parasite that commonly infects a certain type of mosquito which feeds on humans. "Genes in cluster 4, underrepresented in symptomatic malaria and upregulated by asymptomatic infection, included several genes encoding protein products mediating negative regulation of immune processes, such as the anti‐proliferative molecules BTG1 and NDRG2, as well as the checkpoint receptor CD83." (PMID 35475529, 2022).
parasitemia (2 papers, 2013 to 2022). "The relatively high MHCII expression on their surface and the upregulation of APC marker genes including CD83, CD40, and B7-H1 is somewhat surprising since in mammals granulocytes are typically, short-lived effector cells involved in clearance of bacterial and parasitic infections." (PMID 23761795, 2013).
acne (1 paper, 2014). An inflammatory process of the sebaceous glands which is characterized by comedones, nodules, papules and/or pustules on the skin. "We defined the markers of T cell subsets at mRNA level and studied Th1 (T-bet), Th17 (IL-17A), Treg (Foxp3) cells, cytotoxic CD8+ T-cells and CD68 macrophages and CD83 positive activated dendritic cells in clinically early acne lesions by immunohistochemistry both phenotypically and proportionally." (PMID 25153527, 2014). "Importantly, immunohistochemistry revealed significantly increased numbers of IL-17A positive T cells and CD83 dendritic cells in the acne lesions." (PMID 25153527, 2014). "The count of CD4+ cells and CD83+ mature dendritic cells was significantly higher both in the papillary dermis and around follicles in acne lesions, when compared with non-lesional skin." (PMID 25153527, 2014).
acute graft versus host disease (1 paper, 2021). A syndrome of immunologically mediated tissue damage that may occur following an allogeneic transplant, usually affecting the skin, liver, and GI tract. "Studies have shown that anti-CD83 antibodies have immunosuppressive potential thus, they can be used for the treatment of acute graft-versus-host disease (GVHD), which occurs after allogenic hematopoietic stem cell transplant due to the cascades of inflammatory reactions of donor immune cells." (PMID 34267228, 2021).
acute myeloid leukaemia (1 paper, 2020). "Similarly, primary MCL cells expressed more CD83 mRNA transcripts than primary acute myeloid leukaemia cells or healthy donor PBMC." (PMID 32685149, 2020).
adenoma (1 paper, 2025). A neoplasm arising from the epithelium. "Our systematic review has revealed mDC (CD83+, Cd208+) density being slightly decreased in premalignant lesion tissues but significantly decreased in CRC tissues, and the iDCs (CD1α+) density gradually increased from adenoma to carcinoma tissues compared with healthy controls." (PMID 40149674, 2025).
age-related macular degeneration (1 paper, 2021). Age-related loss of vision in the central portion of the retina (macula), secondary to retinal degeneration. "Furthermore, immunochemical examination of human eye samples of age-related macular degeneration showed the presence of the leukocyte antigens CD45, CD4, CD8, CD14, and CD83 in the choroid." (PMID 34963463, 2021).
ampullary carcinoma (1 paper, 2010). "Of note, elevated levels of CD83 positive MDCs and PDCs were also observed in billary duct adenocarcinoma, ampullary carcinoma, and endocrine carcinoma, all cancers in or in connection to the pancreas (data not shown)." (PMID 20976171, 2010).
amyotrophic lateral sclerosis (1 paper, 2020). Amyotrophic lateral sclerosis (ALS) is a neurodegenerative disease characterized by progressive muscular paralysis reflecting degeneration of motor neurons in the primary motor cortex, corticospinal tracts, brainstem and spinal cord. "In amyotrophic lateral sclerosis (ALS) and multiple sclerosis (MS) patients, intrathecal or IV BM-MSC injection increased Treg numbers, reduced lymphocyte proliferation and downregulated the expression of activation and maturation markers such as CD40, CD83 and HLA-DR on DCs." (PMID 32595362, 2020).
Anxiety (1 paper, 2021). Intense feelings of nervousness, tension, or panic often arise in response to interpersonal stresses. "Frequencies of CD40 positive (+) and CD83+ cells were significantly increased in mice under anxiety stress than in control mice (41.80 ± 7.19% vs. 25.94 ± 4.16%, p = 0.008; 27.78 ± 5.45% vs. 11.20 ± 3.88%, p = 0.008, respectively)." (PMID 33868228, 2021).
autism (1 paper, 2025). Persistent deficits in social interaction and communication and interaction as well as a markedly restricted repertoire of activity and interest as well as repetitive patterns of behavior. "The variant lies between the CD83 (384 Kb) and JARID2 (748 Kb) genes, with JARID2 being the likely target given its expression in glutamatergic neurons, critical role in neural development through PRC2 and previous associations with autism and intellectual disability." (PMID 39829783, 2025).
Ba (1 paper, 2022). "Particularly, we previously published results showing that Ba infection induces DCs maturation, as evidenced by the up-regulation of CD86, CD80, CCR7, CD83, MHC-II, MHC-I and CD40 at 24 h post-infection." (PMID 36441810, 2022).
benign tumours of the breast (1 paper, 2003). "The percentage of CD83+ DCs in patients with benign tumours of the breast was absolutely unaffected (3.07 ± 0.92) as compared with controls." (PMID 14562018, 2003).
bone metastasis (1 paper, 2025). Transfer of a neoplasm from its primary site to bones. "Six proteins (CSF-1, CCL4, CCL3, CD83, IL-12, and CD244) and three clinical characteristics (LDH levels, bone metastasis status, and liver metastasis status) were incorporated into the predictive model." (PMID 40404633, 2025).
cat-scratch disease (1 paper, 2012). Cat scratch disease is an infectious illness caused by the bacteria bartonella (Bartonella henselae). "Furthermore, inflammatory cells such MBLs, CD68+, CD163+, CD204+ macrophages, S-100+, Langerin+, CD83+, CD163+ dendritic cells and T lymphocytes can be regarded as playing an important role for granuloma formation in tularemia, as in cat scratch disease." (PMID 22588497, 2012).
chlamydial infection (1 paper, 2008). "CD83 expression is taken as a marker for phenotypic maturation of dendritic cells and higher percentage of DCs expressing them in both Chlamydia positive cases show that during chlamydial infection high number of both mDC and pDC take up antigen for processing and turn into mature DCs." (PMID 18828896, 2008).
chronic endometritis (1 paper, 2022). A non-granulomatous or granulomatous chronic inflammation of the endometrium. "A study on chronic endometritis has shown abundant immune cells in the endometrium and an increase in CD83+ mature DCs, CD68+ macrophages, CD8+ T cells, and Foxp3+ Treg cells; these results might be reasonable for impaired endometrial receptivity and recurrent pregnancy failures." (PMID 36686483, 2022).
CNS demyelinating diseases (1 paper, 2025). "However, the promising results of sCD83 treatment in EAE and the severe disease course of EAE animals lacking CD83, combined with the lack of data on CD83 in NMOSD and MOGAD, highlights the need for further investigation of CD83 in CNS demyelinating diseases." (PMID 40777014, 2025).
co-infection (1 paper, 2019). "In contrast, a reduced maturation of DCs was observed upon co-infection with HIV-C and Chlamydia (HIV-C/Chlam-DCs) and this maturation was comparable to that when iDCs were exposed to HIV-C only (CD83—left panel, CD86—middle panel, HLA-DR—right panel)." (PMID 31178863, 2019).
colonic adenocarcinoma (1 paper, 2020). "Whereas, the TCM from colonic adenocarcinoma significantly inhibited CD54 (p = 0.011), HLA-DR (p = 0.013), CD86 (p = 0.021), CD83 (p = 0.018) and PD-L1 (p = 0.006) compared to LPS-induction in background media alone, cRPMI (+)." (PMID 32552799, 2020).
dementia (1 paper, 2024). Loss of intellectual abilities interfering with an individual's social and occupational functions. "Within the Banner SFG snRNA-seq, we did not observe any difference in age of death, sex, ethnicity, post-mortem interval (PMI), neuritic plaque density, neurofibrillary tangle burden, clinical dementia rating or ApoE4 carriage rates between AD subjects with and without CD83(+) microglia." (PMID 38987616, 2024).
diabetes (1 paper, 2022). "A significant increase of CD83 on classical monocytes was in fact one of the key findings explaining the reduced infection rates with TXA in cardiac surgery patients without diabetes." (PMID 35410340, 2022).
enthesitis (1 paper, 2025). Inflammation at the site of insertion of ligaments, tendons, and other fibrous structures into bone. "Other key genes involved in enthesitis were up‐regulated including CSF2 (encoding granulocyte–macrophage CSF), IL12B, IL6, and notably CD80 and CD83 encoding the M1‐associated costimulatory receptors." (PMID 40320905, 2025).
fertility disorders (1 paper, 2008). "The expression of CD83 on pDCs obtained from women with fertility disorders was significantly higher than that of pDCs obtained from fertile women." (PMID 18828896, 2008).
Fever (1 paper, 2021). Body temperature elevated above the normal range. "In this study, flow cytometry of whole spleen leukocytes, double-stained with anti-CD4-1 and anti–CD83 mAbs, show that the CD83+ population remained relatively invariable in the fever individuals compared with those of the non-infected group after IPNV infection (n = 10, p > 0.05)." (PMID 34445566, 2021).
Fibroadenoma (1 paper, 2011). A benign tumor of the breast characterized by the presence of stromal and epithelial elements. "Positive expression of the CD83 antigen in the epithelial cells of the fibroadenoma (365.52; standard deviation ± 133.13) in relation to the adjacent breast tissue cells (189.59; standard deviation ± 140.75) was statistically larger (P < 0.001)." (PMID 22249796, 2011). "The results showed that, of the factors analyzed, the only one that influenced CD83 expression in breast tissue adjacent to the fibroadenoma was the patient's parity." (PMID 22249796, 2011). "The expression of the CD83 antigen in the fibroadenoma was positive and greater than in the adjacent breast tissue." (PMID 22249796, 2011). "The only feature that presented statistical relevance in relation to CD83 expression was parity and this was only true in relation to the tissue adjacent to the fibroadenoma." (PMID 22249796, 2011). "The expression of CD83 in the fibroadenoma cells was positive and greater than in the breast tissue adjacent to the lump (P < 0.001), when analyzed by means of immunohistochemistry." (PMID 22249796, 2011). "A expressão positiva do antígeno CD83 nas células epiteliais dos fibroadenomas (365,52; desvio padrão ± 133,13) em relação às células do tecido mamário adjacente (189,59; desvio padrão ± 140,75) foi estatisticamente superior (P < 0,001)." (PMID 22249796, 2011). "The value of CD83 expression in the fibroadenoma cells and in the adjacent breast cells was analyzed." (PMID 22249796, 2011). "The main objective of this study was to identify CD83 expression in fibroadenoma cells, since the expression of this antigen is an important marker of maturation of the dendritic cell population and, consequently, an indication of immune activity." (PMID 22249796, 2011). "From analysis on the material from group D (i.e. users of oral hormonal contraceptives), we found an average of 363.25 (SD ± 150.08) cells expressing CD83 in the fibroadenoma, while in the adjacent breast tissue, the average was 191.12 (SD ± 136.71) cells expressing CD83 (P = 0.044)." (PMID 22249796, 2011). "The objectives here were to analyze CD83 antigen expression in human breast fibroadenoma and breast tissue adjacent to the lesion and to identify clinical factors that might influence this expression." (PMID 22249796, 2011). "Positive expression of the antigen CD83 in dendritic cells indicates maturation of these cells and, perhaps, also has the same meaning when expressed in the fibroadenoma epithelial cells, thereby indicating important differentiation between this neoplasia and normal breast tissue." (PMID 22249796, 2011). "The expression of CD83 in the breast tissue adjacent to the fibroadenoma was influenced by whether the patient was nulliparous or had already had at least one full term pregnancy, and it was significantly greater in nulliparous women (P = 0.042)." (PMID 22249796, 2011). "The analysis on the results from groups C and D showed that CD83 expression in the fibroadenoma cells was more evident than in the adjacent breast tissue cells, and that in both groups there was a statistically significant difference in the results (respectively P < 0.001 and P = 0.044)." (PMID 22249796, 2011). "Because of this, knowledge of CD83 expression in breast fibroadenoma cells becomes very important." (PMID 22249796, 2011). "In this context, the repercussions of pregnancy in breast tissue may affect the immune response; this needs to be better characterized, given that CD83 expression in breast tissue adjacent to the fibroadenoma was influenced by the patient's history of pregnancy (P = 0.042)." (PMID 22249796, 2011). "The present study shows that there is increased CD83 expression in fibroadenomas, compared with the adjacent breast tissue (P < 0.001), and this could represent more intense immune activity against these benign tumors, probably mediated by antigen-presenting cells (APC)." (PMID 22249796, 2011).
Fibroadenoma (continued). "This study had two objectives: first, to immunohistochemically analyze the expression of CD83 in human breast fibroadenoma cells and adjacent normal breast tissue; and second, to analyze which clinical features could influence the expression of CD83 in these breast tissues." (PMID 22249796, 2011). "In group C (i.e. non-users of oral hormonal contraceptives), positive CD83 antigen expression was found on average in 366.38 (SD ± 130.11) of the fibroadenoma cells and in 189.00 (SD ± 137.54) of the adjacent breast tissue cells (P < 0.001)." (PMID 22249796, 2011). "Os objetivos são analisar a expressão do antígeno CD83 no fibroadenoma mamário humano e no tecido mamário adjacente à lesão e identificar fatores clínicos que possam influenciar esta expressão." (PMID 22249796, 2011). "A expressão do antígeno CD83 foi positiva e mais expressiva no fibroadenoma do que no tecido mamário adjacente." (PMID 22249796, 2011). "In the fibroadenomas, negative antigen expression or non-expression was observed in 134.14 (SD ± 133.40) of the cells, while in the adjacent breast tissue 310.41 (SD ± 134.85) of the cells did not express the CD83 antigen (P < 0.001)." (PMID 22249796, 2011).
fibrosarcoma (1 paper, 2023). A malignant mesenchymal fibroblastic neoplasm affecting the soft tissue and bone. "Venetoclax also induced other maturation markers including CD80 and CD83 on cDC1 (and cDC2 in some cases) cells from the blood, tumor and both the tumor-draining and non-draining lymph nodes of mice bearing orthotopic MCA205 fibrosarcomas." (PMID 37623817, 2023).
follicular lymphoma (1 paper, 2021). Follicular lymphoma is a form of non-Hodgkin lymphoma characterized by a proliferation of B cells whose nodular structure of follicular architecture is preserved. "Of these, mutations in CREBBP, KMT2D, TNFRSF14 and RRAGC were enriched in follicular lymphoma, and those of BTG2, HLA-A, PIM1, IGLL5, SOCS1, CD83 and SGK1 were enriched in DLBCL." (PMID 33945543, 2021).
gall bladder carcinoma (1 paper, 2024). "Furihata studied the plausible role of CD83 in prognostication in patients with gall bladder carcinoma." (PMID 39529763, 2024).
Hyperglycemia (1 paper, 2022). An increased concentration of glucose in the blood. "The expression of CD83 and CD86 were significantly upregulated in splenic CD11c+ DCs derived from mice with hyperglycemia." (PMID 35062863, 2022).
Hypertension (1 paper, 2018). The presence of chronic increased pressure in the systemic arterial system. "Thus, surface expression of CD209 and CD83 may have functional consequences in enhancing immunogenicity of monocyte-derived cells in hypertension." (PMID 29800237, 2018).
infarction (1 paper, 2020). A localised pathological necrosis of tissue resulting from obstruction of the blood supply usually by a thrombus, an embolus, or vascular torsion. "Similarly, ox‐LDL could further induce the expression of CD83 and CD86 on the basis of Ang II (P < .05), indicating that a high‐fat internal environment can further stimulate the inflammatory mechanism in vivo and aggravate myocardial inflammatory response after infarction." (PMID 32073735, 2020).
laryngeal papilloma (1 paper, 2024). "Researchers have also attempted to correlate laryngeal papilloma with CD83+ DCs." (PMID 39529763, 2024).
malignant glioma (1 paper, 2024). A grade III or grade IV glioma arising from the central nervous system. "Collectively, our data suggest that tumor cell expression of CD83 supports the endogenous antitumor T-cell constituency in malignant glioma." (PMID 39601621, 2024).
mantle cell lymphoma (1 paper, 2020). Mantle cell lymphoma is a rare form of malignant non-Hodgkin lymphoma affecting B lymphocytes in the lymph nodes in a region called the ``mantle zone''. "Our objective was to determine CD83 expression on non‐Hodgkin lymphoma (NHL) and its therapeutic potential to treat mantle cell lymphoma (MCL) which is currently an incurable NHL." (PMID 32685149, 2020).